TTTY9A (testis expressed transcript, Y-linked 9A)
Synonyms: TTY9; NCRNA00131; TTTY9
Gene: Long non-coding RNA gene on chromosome Y (18,729,882 to 18,739,197, forward strand). Ensembl gene ENSG00000290716.
Homologues: Paralogues in human: TTTY9B (100% identical).
Diseases named in the same sentence as TTTY9A in open-access papers:
TTTY9A is named in the same sentence as 1 disease in open-access papers, as found by Europe PMC text mining. Sharing a sentence is not in itself a finding about the gene and the disease.
TTTY9A shares sentences with these, for which no sentence is quoted: Azoospermia (1 paper).